EGFR (epidermal growth factor receptor)
Diseases named in the same sentence as EGFR in open-access papers (continued):
Sharing a sentence is not in itself a finding about the gene and the disease.
tumor (continued). "Associations of the cyclin D1 and EGFR pathway signatures with expression of CCND1 and EGFR, respectively, were also observed in two of the four tumor datasets." (PMID 18350153, 2008). "Here we show that the Hpo tumor-suppressor pathway joins the Notch, EGFR, and JAK-STAT pathways in regulating follicle-cell patterning and oocyte AP polarity formation." (PMID 18335037, 2008). "Recently, it was reported that nuclear expression of FABP7 is restricted to infiltrative tumor types and related to EGFR amplification and over-expression as well as poor prognosis of GBM." (PMID 18826602, 2008). "In our combined analysis of VEGF and EGFR expression, both markers had independent value for predicting a complete pathologic tumour regression." (PMID 18182986, 2008). "As a similar (∼80%) and significant reduction of EGFR and mTOR occurred after combination therapy, it is most likely that this dual suppression is a key mechanistic component of the observed tumour suppression." (PMID 18797454, 2008). "We initially examined EGFR expression in both cell lines and found that EGFR is present as aggregates in the tumor cell nuclei as well as localized to the plasma membrane and cytoplasm." (PMID 18177496, 2008). "It is known that NSCLC patients with EGFR-dependent primary tumours when treated with TKIs can develop metastases, in which either the EGFR signalling is negated or resistance is acquired due to secondary EGFR mutations like T790M or MET amplification." (PMID 19238633, 2008). "The relation between the tumour stage and the degree of staining for Id-1, EGFR and VEGF was also significant." (PMID 19014499, 2008). "EGFR mRNA correlated with tumor size (p < 0.05), tumor number (p < 0.05), recurrence (p < 0.05) and clinical stage (p<0.05)." (PMID 21892326, 2008). "Despite the relatively small number of patients for whom the primary tumor was available for EGFR evaluation, it was evident that an EGFR-negative primary tumor does not preclude the presence of EGFR-expressing CTCs." (PMID 18822183, 2008). "Several clinical trials demonstrating the efficacy of VEGF inhibition for other cancers have been reported, and VEGF upregulation in tumour cells is considered to be a mechanism of resistance to EGFR inhibitors." (PMID 18087285, 2008). "Over the past years, there has been a proliferation of agents designed to inhibit single PTK in tumor, including those directed against Bcr-Abl (e.g. imatinib mesylate), epidermal growth factor receptor (EGFR, e.g. erlotinib), HER-2/neu (e.g. trastuzumab)." (PMID 19020661, 2008). "Patients with tumours that express mutant EGFR derive a significant benefit from minimally toxic targeted therapy such as gefitinib and erlotinib." (PMID 22275966, 2008). "The aim of this study was to examine the anti-tumour effects of the clinically representative anti-angiogenic monoclonal antibody bevacizumab combined with the anti-EGFR tyrosine kinase inhibitor erlotinib and RT." (PMID 18577994, 2008). "Twenty-seven (19%) patients had EGFR–FISH positive tumours and 31 (22%) had EGFR-IHC positive tumours." (PMID 18283317, 2008). "Inhibition of EGFR or VEGFR-2 signaling by gefitinib or vandetanib is inadequate to inhibit tumor cell proliferation in vitro other than through unspecific toxicity." (PMID 18177496, 2008). "In fact, everolimus is not only effective in tumour cells with acquired resistance to anti-EGFR drugs, but it is also able to induce a re-sensitisation against this class of inhibitors." (PMID 18319715, 2008). "Owing to the wide range of different tumour subcategories and levels of EGFR expression within basal-like tumours, it is significant that we can demonstrate here the effectiveness of silencing TNK2 even when the EGFR pathway is active but not hyperactivated." (PMID 18435854, 2008). "Zalutumumab, a high-affinity human IgG1K EGFR antibody, potently inhibits tumor growth in xenograft models by engaging two mechanisms of action." (PMID 18702090, 2008).
tumor (continued). "An example of this is the development of EGFR tyrosine kinase inhibitors in the management of NSCLC patients where the presence of predictive markers such as EGFR and KRAS mutations in their tumours stratifies patients to receive the appropriate treatment." (PMID 18495026, 2008). "As our findings in NSCLC cell lines suggested concurrency of KRAS or BRAF and mutual exclusiveness of EGFR mutations with LKB1 mutations, we analysed the mutational status of these genes in our primary NSCLC tumour specimens." (PMID 18594528, 2008). "Increased levels of ErbB3, Tyr1289-phosphorylated ErbB3, epidermal growth factor receptor (EGFR) and ErbB4 were readily detected in the c-ErbB2 tumours compared with normal tissue from the same mice." (PMID 18700973, 2008). "Recently, we have shown that NCX-4016 suppressed the growth of cisplatin-resistant human ovarian xenograft tumor (A2780 cDDP) in mice by inducing G1 cell-cycle arrest and apoptosis though inhibition of EGFR/PI3K and STAT3 signaling pathways." (PMID 18302761, 2008). "It has been reported that the overexpression of the EGFR in RCCs plays a role in the development and progression of the tumor and is frequently accompanied by high grade tumors." (PMID 18928570, 2008). "EGFR is overexpressed in several human tumours and is considered to initiate a variety of important steps during the malignant transformation." (PMID 18985033, 2008). "The epidermal growth factor receptor (EGFR) plays a key role in tumour growth, angiogenesis, and metastasis in NSCLC." (PMID 18283317, 2008). "In a preclinical study, nimotuzumab showed marked antiproliferative, proapoptotic, and antiangiogenic effects in tumours that overexpress EGFR." (PMID 18253126, 2008). "When injected into mice harbouring IGFR‘+’/EGFR‘+’ HT-29 tumour xenografts, the di-diabody elicits an anti-tumour response that was statistically similar to that seen in mice treated with a combination of both parent antibodies." (PMID 18841159, 2008). "Tumour samples were analysed for EGFR protein expression by immunohistochemical analysis and for EGFR gene amplification by fluorescence in situ hybridisation (FISH), chromogenic in situ hybridisation (CISH) and NF-kB activation." (PMID 18059397, 2008). "The odds of complete response were 12.8 for the multi-marker combination of VEGF-negative and EGFR-positive tumours." (PMID 18182986, 2008). "Complete pathologic response was nearly six times more likely in EGFR-positive tumours compared with EGFR-negative cases." (PMID 18182986, 2008). "In three out of 12 (25%) and four out of 10 (40%) there was a discrepancy in EGFR expression between the primary tumor and CTCs in early and metastatic breast cancer, respectively." (PMID 18822183, 2008). "In the present series, we showed that high expression of EGFR waspresent in the high-grade areas of the tumours, appearing to colocalize with Ki-67 in all cases and with p53in half of the cases." (PMID 18769552, 2008). "We recently observed that NCX-4016, an isomeric form of NCX-4040, inhibited tumor growth by modulating EGFR/PI3K and STAT3 signaling pathways." (PMID 18302761, 2008). "The number of tumors (p < 0.05), tumor size (p < 0.05), recurrence (p < 0.05) and clinical staging (p < 0.05) were significantly correlated with EGFR mRNA expression." (PMID 21892326, 2008). "We determined EGFRvIII status by immunohistochemistry using the well-defined antibody DH8.3 and verified our results at the RNA level by RT–PCR on a subset of 45 tumours showing positive immunostaining for EGFR or downstream targets." (PMID 18628764, 2008). "Concordance between the primary tumour and the corresponding metastases was observed in 17 (89.5) patients (Cohen's Kappa=0.729, P=0.001) and among them EGFR was overexpressed in four (21.1%)." (PMID 19238633, 2008).
tumor (continued). "c-ErbB2 tumours demonstrate overexpression of EGFR, ErbB2, ErbB3 and ErbB4, and activation/phosphorylation of both ErbB2 and ErbB3, underscoring the importance of the entire EGFR family in ErbB2-induced tumourigenesis." (PMID 18700973, 2008). "Irradiation of tumour cells has been shown to activate EGFR via ligand-independent and ligand-dependent mechanisms, possibly accounting for radiation-induced acceleration of tumour cell repopulation and the development of radioresistance." (PMID 18253126, 2008). "A correlation between EGFR expression by Western blot analysis and %ID/g in the various tumor types was observed, suggesting that 64Cu-DOTA-cetuximab is a potentially accurate biomarker for EGFR expression." (PMID 18991714, 2008). "We demonstrated that EGFR and pEGFR are both expressed in the membrane of 11.3% and 35.7% of tumour cells." (PMID 18522728, 2008). "Although 15 changes were observed, only 4 patients with EGFR overexpression in the primary tumor had lower EGFR scores in the corresponding lymph node metastases." (PMID 18700025, 2008). "Tyrosine kinase inhibitors of EGFR have been shown to efficiently block the in vitro and in vivo activation of this receptor, and to significantly inhibit tumor growth in experimental animal models." (PMID 18320059, 2008). "EGFR overexpression in tumor cells can produce up to 2 million EGFR molecules per cell, and has been correlated to a more malignant tumor grade as well as a reduced patient survival." (PMID 18702090, 2008). "Consequently, the EGFR gene status could be classified as: (i) EGFR wild type in both primary tumour and metastasis (n=18 patients; 72%), and (ii) EGFR mutations detected only in the primary tumour (n=4 patients; 16%) or the metastases (n=2 patients; 8%) or both (n=1 patient; 4%)." (PMID 19238633, 2008). "Tumours with <85% EGFR staining had a significantly better survival time (87.0 months (69.0–103.0)) (P<0.001) compared to tumours overexpressing the protein (35.0 months (23.0–58.0))." (PMID 17311026, 2007). "Based on preclinical findings, it should be outlined that the trials including cetuximab have been performed in patients who expressed EGFR protein in primary tumours based on immunohistochemistry (IHC)." (PMID 17940504, 2007). "A tumour was defined as EGFR positive if the ligand binding was >10 fmol mg−1 protein and showed positive staining for EGFR by immunohistochemistry." (PMID 17311025, 2007). "The epidermal growth factor receptor (EGFR) is expressed at much higher levels in SCCHN tumours than in normal epithelial tissue, and EGFR expression correlates with poor prognosis." (PMID 17224925, 2007). "The use of HIF-1α as an indicator of tumor response to EGFR-targeted therapy should be further investigated in preclinical studies and in the clinical setting." (PMID 17931419, 2007). "Next, we examined HER-2 and EGFR expression in freshly isolated tumours (primary tumour and malignant pleural effusion) derived from six different oesophageal SCC patients." (PMID 17622245, 2007). "In clinical tissue all samples demonstrated cytoplasmic tumour epithelial HRGβ1 protein staining, with expression correlating with EGFR positivity and activation of both AKT and ERK1/2." (PMID 17686159, 2007). "A multi-scale agent-based model has been developed by Deisboeck and colleagues over the past several years to investigate the relationship between EGFR dynamics, tumor cell proliferation and cell migration." (PMID 19936081, 2007). "In this tumor, the Ct value difference was >2 between qPCR fragments inside (measuring only wild-type EGFR transcripts) and outside (measuring both wild-type and EGFRvIII transcripts) the EGFR exon 2–7 deletion region." (PMID 18688287, 2007). "Complete pathological response was more than seven times more likely to occur in tumours overexpressing EGFR whereas complete or partial response was found to occur nearly four times more often in these cases." (PMID 17311026, 2007).
tumor (continued). "Seven tumours were identified as FISH+ for EGFR amplification and four tumours were identified as FISH+ for HER2 amplification (high polysomy or gene amplification)." (PMID 17626639, 2007). "Epidermal growth factor receptor expression was positive in 51 (52%) primary tumours and 45 (45%) metastatic sites." (PMID 17579627, 2007). "On the other hand, it is known that a portion of the membrane receptor is shed into the bloodstream thus making plasma or serum an excellent source, best than tumour tissues, to evaluate dynamic variations of the EGFR since the diagnosis and during treatment." (PMID 17453000, 2007). "The microvessel count was higher in tumours overexpressing EGFR than in EGFR-negative tumours (11.5 vs 6; P<0.001), and in tumours >2 cm than in those ⩽2 cm (10 vs 6.5; P=0.001)." (PMID 17609662, 2007). "These analyses identified multiple EGFR-associated profiles in vivo that were of prognostic significance, showed important links with tumor subtype, and highlight potential downstream activators of the EGFR-RAS-MEK pathway." (PMID 17663798, 2007). "All patients had EGFR-positive tumours at IHC, five cases (19%) were classified as score 1+, nine cases (33%) as score 2+ and 13 (48%) as score 3+." (PMID 17940504, 2007). "Correlative scientific data from tumour biopsies in some of these studies confirm that TKIs reach their molecular targets and suppress the activity of EGFR and HER2 and downstream MAPK signalling." (PMID 17667926, 2007). "The association between the presence of EGFR mutations and response to TKIs has been confirmed through the analysis of thousands of NSCLC tumor samples worldwide." (PMID 17877814, 2007). "Increased gene copy number was observed in thirteen tumours, seven with EGFR amplification, three with HER2 amplification, and three with amplification of both genes." (PMID 17626639, 2007). "Overexpression of EGFR (>85% tumour cell staining) was more frequently found in tumours with late T stage, although this difference was only marginally significant (P=0.069)." (PMID 17311026, 2007). "Tumour extracts from both lines had detectable phosphorylated EGFR immunoreactivity, but RWGT2 extracts produced more intense bands." (PMID 17533397, 2007). "Histologic tumor studies were done by haematology and eosin staining and EGFR-overexpression was measured by EGFR Pharm Dx kit K 1494 (Dako Cytomation)." (PMID 17927839, 2007). "Among the standard techniques such as protein expression, RNA transcript and DNA assays used to detect EGFR expression in tumours, immunohistochemistry (IHC) is the most commonly used in CRC." (PMID 17311026, 2007). "The activated EGFR also regulates the production of angiogenic factors and permits tumour invasion through extracellular matrix components." (PMID 17940504, 2007). "EGFR gene amplification was determined in 3.5% of tumours showed and correlated with EGFR expression for only three antibodies." (PMID 17915016, 2007). "Microvessel density was associated with epidermal growth factor receptor (EGFR) expression (P<0.001) and tumour size (P=0.001)." (PMID 17609662, 2007). "In our experiments, we showed that not only are the basal-like tumor derived cell lines the most sensitive to carboplatin and the EGFR inhibitors when applied individually, but also that the combination was synergistic." (PMID 17663798, 2007). "In this paper, we demonstrate that activation of the proapoptotic BH3-only protein BIM is essential for tumor cell killing and that shutdown of the EGFR–MEK–ERK signaling cascade is critical for BIM activation." (PMID 17973573, 2007). "The presence of membranous staining for EGFR and/or ErbB2 was significantly correlated with tumour phenotype." (PMID 17700572, 2007).
tumor (continued). "In particular, increasing the expression of these growth factors leads to EGFR hyperactivity, thus increases tumor cell motility and invasiveness, and finally enhances lung metastasis." (PMID 18154660, 2007). "Exactly how inhibition of EGFR signaling results in the often dramatic tumor responses of EGFR-mutant lung tumors has remained an enigma." (PMID 17973575, 2007). "While both of these methods identified seven tumours with EGFR amplification, the EGFR/CEP7 ratio ≥ 2 method identified an additional three tumours which were classified as "Low Polysomy" under the Cappuzzo criteria." (PMID 17626639, 2007). "A marginally significant difference in tumour grade with EGFR overexpression was observed (P=0.051)." (PMID 17311026, 2007). "The distribution of EGFR scores in both study groups varied considerably with those in Study group 1 ranging from 0 to 90% with only 5% of tumours expressing EGFR in more than 80% of tumour cells." (PMID 17311026, 2007). "Cetuximab (IMC-C225) has antitumour activity against several tumour cell lines expressing EGFR and in SCC tumour xenograft models." (PMID 17224925, 2007). "Recently, tumours that overexpress the EGFR have been challenged with the anti-EGFR therapies currently approved." (PMID 17453000, 2007). "EGFR membrane expression was assessed by immunohistochemistry in all tumour specimens; A total of 42 (49%) of these specimens were considered as positive (2+ or 3+) for EGFR expression." (PMID 18000506, 2007). "An increasing number of studies examining the tumours of patients treated with gefitinib and erlotinib have correlated increased EGFR gene copy number with response." (PMID 17626639, 2007). "For instance, autocrine EGFR-mediated motility promotes tumour invasion and metastasis and tumour cell proliferation and survival." (PMID 17406365, 2007). "Aberrant activation of the epidermal growth factor receptor (EGFR) is frequently observed in neoplasia, notably in tumours of epithelial origin." (PMID 17716369, 2007). "The model confirmed previous experimental findings that increasing EGFR density on the cell surface correlates with an increase in the rate of tumor expansion." (PMID 19936081, 2007). "EGFR expression was upregulated after induction of hEGR1 during hypoxic exposure of human tumour cells (U-2OS) and it was found that hEGR1 directly induced EGFR transcription." (PMID 17311025, 2007). "Gene copy number was assessed in our patient tumour samples as previous studies have shown a correlation between copy number increases in EGFR or HER2 and gefitinib response." (PMID 17626639, 2007). "Further investigation of the intracellular signalling pathways involved in the hEGR1 induction by EGF and its inhibition by gefitinib would clarify the role of hEGR1 in EGFR-dependent tumour growth and progression and its inhibition by gefitinib." (PMID 17311025, 2007). "Another study examined the possible mechanisms of resistance to the EGFR inhibitor ZD1839 (Iressa) in tumor cells with variable levels of EGFR." (PMID 19384426, 2007). "Epidermal growth factor receptor (EGFR) is highly expressed in many tumours, including those of the cervix, and there is a clear relationship between HPV E6/E7 oncoproteins and EGFR function." (PMID 17242701, 2007). "Epidermal growth factor receptor phosphorylation in tumours was measured by Western blots with the EGFR phosphotyrosine-specific antibody to residue 1068." (PMID 17533397, 2007). "Sixty-six oesophageal SCC tumours were examined for both EGFR and HER-2 expression in serial sections by IHC." (PMID 17622245, 2007). "Hyperactivation of MAPK was associated with both ER status and tumour phenotype by unsupervised hierarchical clustering using the MAPK signature and was significantly reflected by overexpression of EGFR and/or ErbB2." (PMID 17700572, 2007).